TLR4 (toll like receptor 4)
Diseases named in the same sentence as TLR4 in open-access papers (continued):
Sharing a sentence is not in itself a finding about the gene and the disease.
Obesity (continued). "Another driver of obesity-related inflammation is the activation of toll-like receptors (TLRs), especially TLR-2 and TLR-4." (PMID 37036026, 2023). "In the context of obesity, TLR2 and TLR4 act as significant mediators that connect excessive food intake and the occurrence of inflammation." (PMID 38276294, 2023). "Activation of TLR4 by fatty acids, especially palmitic acid, is a key mediator between the HFD-induced inflammatory response and obesity and insulin resistance." (PMID 37028769, 2023). "Compared to the control group, in monocytes the obesity group expressed higher TLR4, CD36, and NF-κB p65 in lymphocytes, the obesity group expressed higher TLR4 and CD36; and in granulocytes the obesity group expressed higher CD36." (PMID 37403139, 2023). "LPS is a potent agonist of Toll-Like Receptor 4 (TLR4), considered a part of the etiopathology of obesity and T2DM." (PMID 37082122, 2023). "We then assessed the protein of Toll-like receptor 4 (TLR4, p < 0.05) under these changes brought on by HFD, which regulates obesity-induced inflammation and metabolic dysfunction." (PMID 37237884, 2023). "In contrast, genetic deletion of the LPS receptor, the toll-like receptor 4 (TLR4), confers to resistance against high caloric diet-induced obesity, improves glucose tolerance and insulin sensitivity, and promotes adipose tissue browning." (PMID 35259160, 2022). "Obesity is characterized by low-grade chronic inflammation, possibly triggered by TLR2 and TLR4 activation." (PMID 35721808, 2022). "When mimicking obesity in a mouse model, deletion of MD1 aggravated high-fat diet-fed induced maladaptive left ventricular hypertrophy via TLR4/MyD88/CaMKII and TLR4/NF-kB signaling." (PMID 35237675, 2022). "As a result, this research was performed to explore their effect on FATP4 and TLR4 in adipose tissue and liver tissue in a rat model of HFD-induced obesity." (PMID 36360622, 2022). "The anti-obesity effects of GFPA were found to be related to the inhibition of Cer, via the downregulation of TLR4-mediated pro-inflammatory signaling cascades in mice with DIO." (PMID 35967316, 2022). "We also studied the role of TLR2 and TLR4 in the development of mature onset obesity and insulin resistance by using TLR2−/− and TLR4−/−, as well as TLR2−/−-TLR4−/− mice." (PMID 36555322, 2022). "Immunohistochemistry analysis showed that TLR4, IRAK1 and NF-kB were significantly upregulated in individuals with obesity." (PMID 36552771, 2022). "We have observed that obesity induced a remarkable increase in TLR2 gene expression in both PBMC and PMN while TLR4 mRNA levels remained unchanged." (PMID 35896710, 2022). "LPS- and FFA-mediated TLR4 activation in WAT plays a key role in activating pro-inflammatory signaling and thus obesity-dependent insulin resistance." (PMID 33805912, 2021). "LPS signaling via Toll like receptor 4 (TLR4) was found to reduce Gpr81 transcription in mouse WAT, making it plausible that impaired lactate signaling contributes to obesity." (PMID 34571937, 2021). "Increased protein expression of TLR4 protein in monocytes of WBC in obese subjects highlighted the role of TLR4 as a connection among inflammation, IR and obesity." (PMID 32708841, 2020). "In contrast, brain knockout or central pharmacological inhibition of TLR4 or IKKβ/NF-κB prevents hypothalamic inflammation, improves leptin sensitivity and protects against HFD-induced obesity." (PMID 32760236, 2020). "Thus, TLR4 could be the missing connection among inflammation, IR and obesity." (PMID 32708841, 2020). "Palmitic acid is a stimulator of toll-like receptor 4 (TLR4) signaling pathways in monocytes/macrophages and contributes to obesity-related chronic inflammation and insulin resistance." (PMID 33050324, 2020). "Tenascin C is also related to activation of the toll-like receptor 4 (TLR4) signaling pathway, which triggers the obesity-induced inflammatory response." (PMID 32485856, 2020).
Obesity (continued). "Moreover, the decrease in TLR4 expression in exercised obese animals could be related to the anti-inflammatory effects of exercise previously observed by our group in the same animal model of obesity." (PMID 32429330, 2020). "Resistin promotes hypothalamic neuroinflammation and insulin resistance through Toll like receptor 4 (TLR4), this hormone is thought to be a link between obesity and insulin-resistance." (PMID 30845245, 2019). "Future studies should focus on the TLR4‐ and DAP12‐dependent mediators of obesity‐induced cartilage catabolism." (PMID 31044181, 2019). "In molecular, LPS-mediated TLR4/CD14 pathway has been recognized as the main mechanism linking gut microbiota and obesity." (PMID 31374958, 2019). "The current study is the first to directly test the effect of both Tlr4 and Cd14 gene knock-outs on HFD-induced obesity in the same study." (PMID 30353127, 2018). "This study also identified IL-6 and IL-10 as markers of TLR4 activation in HCC and subjects with NAFLD and obesity as the target population who would benefit from TLR4 inhibition treatment for HCC chemoprevention." (PMID 30034633, 2018). "This study demonstrated the promise of using a TLR4 inhibitor such as resatorvid for HCC chemoprevention and suggested that patients with obesity, diabetes and/or NAFLD should be the target population for this chemoprevention approach." (PMID 30034633, 2018). "In conclusion, we demonstrate that specific down-regulation of TLR4 expression in the hypothalamic ARC is sufficient to improve glucose and lipid homeostasis during the course of diet-induced obesity by inhibition of hypothalamic inflammation." (PMID 28785099, 2017). "The impact on the regulation of body mass was not as impressive as the effects obtained when other anti-inflammatory approaches are used to dampen obesity-induced hypothalamic inflammation, such as the inhibition of JNK, IKK, TLR4, or ERS." (PMID 28446241, 2017). "Our findings demonstrated that metformin significantly decreased the TLR4 level on monocytes originating from all NAFLD patients in a dose-dependent manner; however, its efficacy depended largely on the presence of obesity." (PMID 26930651, 2016). "Both NAFLD and obesity are characterized by increased circulating endotoxin and FFA levels as well as enhanced TLR4 expression on liver cells (mainly Kupffer cells) and blood leukocytes (mainly monocytes)." (PMID 26930651, 2016). "Recognition of LPS by Toll-like receptor 4 (TLR4) of host cells triggers downstream inflammatory events that contributes to the development of obesity and metabolic disorders such as insulin resistance." (PMID 26938554, 2016). "Obesity leads to the enhanced expression of TLR2 and TLR4 on the peripheral blood mononuclear cells which has significant implications with regard to inflammation." (PMID 26312071, 2015). "Therefore, our objectives were: 1) to determine whether mice that lack functional TLR4 will be protected against peripheral and cardiac derangements in glucose homeostasis during HFD-induced obesity and, 2) to identify the underlying intracellular signaling pathways." (PMID 26539824, 2015). "Ablation of various pattern recognition receptors (PRRs) such as TLR4, CD14, PKR, and NLRP3 protect mice from diet-/obesity-induced inflammation and insulin resistance." (PMID 25666722, 2015). "The magnitudes of the obesity-induced upregulation of the TLR1, TLR4, TLR5, TLR8, TLR9, and TLR12 genes in the visceral adipose tissue were even greater in the diet-induced obesity (DIO) mice than in the ob/ob mice." (PMID 26681840, 2015). "In conclusion, unsaturated fatty acids can reproduce a number of the anti-inflammatory effects of TLR4 or TNF-α inhibition and, therefore, constitute an attractive nutritional approach to treat obesity." (PMID 22279596, 2012).
Obesity (continued). "Therefore, beside TLR4, other toll-like receptors are differentially expressed in human fat tissue, and functional in an adipocyte cell line, suggesting that they might participate omental adipose tissue-related inflammation that occurs in obesity." (PMID 20339530, 2010). "A series of reports are in favor of a role of LPS, mainly through TLR4 and CD14, in obesity induced NAFLD." (PMID 21042596, 2010). "Innate immunity receptors, such as Toll-like receptor (TLR)-4 and -2, are expressed in WAT (particularly by adipocytes, preadipocytes, macrophages, and endothelial cells) and are involved in this obesity-related inflammatory process." (PMID 20671929, 2010). "RT-qPCR results showed that, compared with the control group, mRNA expression levels of VEGFA, VEGFR-2, CD31, and SIRT1 were significantly decreased in the obesity group (P < 0.001), while the expression levels of GLUT1, HIF-1α, TNF-α, IL-6, HMGB1, and TLR4 were significantly upregulated (P < 0.01)." (PMID 41505418, 2026). "HFD-induced obesity resulted in a marked attenuation of EFS-evoked contractile responses in both genotypes, with maximal contractions at 40 Hz decreased by 42% in WT and 34% in TLR4−/−." (PMID 41226745, 2025). "Next, we investigated the TLR4/NF-κB signaling during obesity and related inflammation in the absence of siglec-E." (PMID 39967660, 2025). "Under physiological conditions, TLR4−/− mice display altered gut motility and changes in ENS neuronal composition in both the small intestine and colon, yet they are protected from obesity-induced inflammation and insulin resistance." (PMID 41226745, 2025). "In T2DM and obesity, the increase in TLR4 activation is due to saturated non-esterified fatty acids and LPS acting as ligands." (PMID 40076851, 2025). "There were some sex differences in the expression of monocyte activation markers: in children with obesity, expression (MFI) of CCR2, CD11b, CD11c, TLR2 and TLR4 were higher in females than males indicating that monocytes in female children with obesity have a more pro-inflammatory phenotype." (PMID 38741712, 2024). "Additionally, TLRs‐induced inflammation plays an important role in obesity, and metabolic syndrome, especially TLR2 and TLR4." (PMID 39073297, 2024). "TLR4 activation enhances metabolic inflammation and insulin resistance and TLR2 via its activation by molecules derived from the gut microbiota favours the onset of obesity." (PMID 41853552, 2024). "Pathways identified as important in inflammation, as related to diet and obesity, include the NLRP3 inflammasome, macrophage-mediated chronic low-grade inflammation in adipose tissue, and the toll-like receptor 4 (TLR4) signaling pathway that is activated by saturated fatty acids." (PMID 38978699, 2024). "Obesity induced by a high‐fat diet increases PA levels, which can upregulate the expression of intracellular TLR2 and TLR4, generate reactive oxygen species (ROS), increase NF‐κB activity, induce the expression and activity of Toll‐like receptors (TLR), and release inflammatory factors." (PMID 39207121, 2024). "Nevertheless, we also observed changes in cytokine release in monocytes from donors with obesity after LPS i.e. TLR4 stimulation, whereby TNF, IL-6, and IL-1 were not affected, while IL-8 was increased." (PMID 39050851, 2024). "Recent studies have identified the MD-2/TLR4/NF-κB axis as a key mechanism in HFD- and obesity-related renal damage, suggesting that targeting this pathway may provide a novel approach to mitigating HFD-induced nephropathy." (PMID 39765652, 2024). "This also confirmed that female mice and the knockout of TLR4 were not compatible with reaching the obesity criterion." (PMID 38275739, 2024). "In TLR4‐KO mice, HFD also caused obesity and gut dysbiosis but did not increase cognitive impairment or WML severity after BCAS." (PMID 37287396, 2023).
Obesity (continued). "The LPS can promote the inflammation of adipocytes via Toll-like receptor 4, resulting in the dysfunction of glucose transport into adipocytes via insulin-dependent glucose transporter type 4 (GLUT4), which mimics insulin resistance in human obesity." (PMID 37297501, 2023). "Obesity-related inflammation is possibly induced by TLR2 and TLR4 activation." (PMID 38203423, 2023). "Changes in the fatty acid receptor CD36, inflammatory receptor TLR4, and inflammatory nuclear transcription factor NF-κB p65 in PBMC subsets were used to further test the relationship between fatty acids and the inflammatory state in individuals with obesity." (PMID 37403139, 2023). "It has been reported that only female mice lacking TLR4 showed increased obesity but partially protected against HFD-induced obesity and insulin resistance, accompanied by less liver and fat inflammation compared with control mice." (PMID 37028769, 2023). "MiR-223 has been found to be increased in populations with obesity and insulin resistance; furthermore, this miRNA was found to modulate the inflammatory phenotype and macrophage activation through the FBXW7/TLR4 (F-box and WD repeat domain containing 7/toll-like receptor 4) axis." (PMID 38132872, 2023). "Animals lacking TLR4 are relatively protected from HFD induced obesity and diabetes, whereas animals lacking TLR5, on the other hand, have an increased risk of obesity." (PMID 38140398, 2023). "Mouse studies have revealed that nonfunctional mutant TLR4 leads to reduced obesity-related symptoms and inflammation, suggesting that TLR4 plays a pivotal role in diet-induced obesity and metabolic disturbances." (PMID 38276294, 2023). "As NASH progression is believed to be linked to gut dysbiosis and gut-derived signals, and especially LPS and its receptor TLR4, we first investigated if gut-derived TRL particles might be containing LPS in obesity and NAFLD." (PMID 36766683, 2023). "Based on our results in the colon, liver and brain, we speculate that quinoa plays an anti-obesity role through gut microbiota acting as an important mediator of the microbiota-gut-brain-liver axis that is regulated by TGR5, GLP-1, and TLR4." (PMID 35583337, 2022). "In obesity and aging, high plasma levels of free fatty acids (FFA) and increased concentrations of lipopolysaccharide (LPS) from gut microbiota (due to increased permeability of gut), bind to Toll-like Receptor 4 (TLR4)." (PMID 36235130, 2022). "Specifically, TLR4/TLR2 have emerged as metabolic sensors of lipopolysaccharide (LPS) and saturated free fatty acids (sFFAs), both of which are abundantly found in individuals with obesity and T2D." (PMID 36552771, 2022). "TLRs, especially, the TLR4 and TLR2 have emerged as key players in metabolic inflammation by nutrient sensing of LPS as well as sFFAs, both of which are abundantly found in individuals with obesity/T2D." (PMID 36552771, 2022). "In this study, when TLR4 was knocked down, we did not obserevd apparent improvements on hepatic steatosis, inflammatory response, gut barrier function and obesity in Sin A-treated NAFLD mice." (PMID 36132991, 2022). "In addition, a large amount of dietary n‐3/n‐6 PUFAs ameliorated obesity‐related insulin resistance and inflammation by inhibiting the activation of TLR4 in rats, prompting us to speculate whether n‐3 PUFAs could suppress depression by regulating TLR4 and its related signaling pathways." (PMID 36301036, 2022). "Despite tangible differences between viral and bacterial infections, they share some major molecular signaling cascades, such as an increment in expression and activation of TLR-4 and SAA pathways, conceivably indicating the link between acute inflammation and the development of obesity." (PMID 35335996, 2022). "On one hand, the activation of TLR4 signal in AgRP/NPY and POMC neurons decreased the expression of AgRP/NPY and increased the expression of POMC, which induced the reduction of appetite and suggested to be involved in obesity." (PMID 34899611, 2021).
Obesity (continued). "Leptin, TGF-β1, and TLR4 pathway through PREP1 reduction or increased IL-6 expression could be promising new biological markers and therapeutic targets in obesity-related diseases." (PMID 34327205, 2021). "Moreover, TLR4-NF-κB can regulate the activation of NLRP3 inflammatory bodies and participate in various inflammatory diseases, such as hepatic lipid metabolism in obesity." (PMID 34760017, 2021). "In the occurrence and development of obesity-related OA, SOCS3 may be a key factor in the regulation of TLR4 signaling by leptin." (PMID 34457118, 2021). "In addition, other studies showed that gut dysbiosis promotes a state of metabolic endotoxemia during obesity, resulting in blood LPS accumulation, metainflammation and insulin resistance through CD14/TLR4 pathway." (PMID 32903730, 2020). "In summary, our results show that cooperative effect of stearic acid on the TNF-α induced production of MIP-1α/CCL3 depends on TLR4-TRIF-TBK1-IRF3 signaling cascade which suggests an interesting pathophysiological link among stearic acid, TNF-α, and MIP-1α/CCL3 in the state of obesity." (PMID 33050324, 2020). "Some controversy regarding the role of LPS in obesity arose when Dalby and colleagues did not detect any protection against increased body weight in studies performed in TLR4 knockout mice, which were unresponsive to LPS signaling." (PMID 32106469, 2020). "Similarly downstream of TLR4, IRF3 promotes AT inflammation upon diet-induced obesity and inhibits adipose tissue browning." (PMID 32140136, 2020). "Consequently, more lipopolysaccharides (LPS) are released from the gut, which initiates toll-like receptor-4 (TLR4) signaling and inflammatory response, contributing to the development of obesity and T2D." (PMID 30984260, 2019). "To test the hypothesis that TLRs contribute to the development of obesity in offspring with prenatal LPS exposure (offspring-pLPS), we analyzed the mRNA expression levels of two well-studied TLRs, TLR2, and TLR4." (PMID 31507457, 2019). "Toll-like receptor 4 (TLR4) is known as a component of immune system pattern recognition receptors (PRRs) and plays a crucial role as a trigger of metabolic inflammation and insulin resistance during obesity." (PMID 31933540, 2019). "LPS can bind and activate TLR-4 to increase the expression of pro-inflammatory mediators such as TNF-α, and these pro-inflammatory mediators can interfere with the binding of insulin to its receptor, leading to IR and obesity." (PMID 30744700, 2019). "On the other hand, activation of TLR-4 in adipose tissues occurs through interactions with gut microbiota LPS or adipocyte lipolysis-released free fatty acids, which can induce the secretion of inflammatory adipocytokines (i.e., IL-6 and TNF) in obesity." (PMID 31632356, 2019). "Overall, 12‐weeks of HFD treatment induced significant obesity in aged female mice independent of TLR4 or DAP12 deletion." (PMID 31044181, 2019). "Combined treatment of PA and LPS in RAW264.7 cells mimics the situation of diabetes with obesity that has higher level of PA and LPS, MAPK/TLR4/ MCP-1 might be potential therapeutic targets for diabetes with obesity." (PMID 30909920, 2019). "We found that aged female TLR4 KO mice treated with HFD for 12 weeks developed significant obesity and glucose intolerance, although not as severe as WT mice, with associated hyperinsulinemia." (PMID 31044181, 2019). "MiR-223 has been well documented to connect insulin resistance and inflammation, and controls multifactorial signals connected with F-box and WD repeat domain containing 7 (FBXW7), toll-like receptor 4 (TLR4), and STAT to alleviate insulin resistance and obesity pathogenesis." (PMID 31847392, 2019). "We undertook this study to test the hypothesis that TLR4 promotes, whereas DAP12 limits, obesity‐accelerated OA in aged female mice." (PMID 31044181, 2019).